AR (androgen receptor)
Diseases named in the same sentence as AR in open-access papers (continued):
Sharing a sentence is not in itself a finding about the gene and the disease.
cancer (continued). "EGCG has been found to affect several cancer-related proteins including Cyclin-dependent kinase inhibitor p27 (p27), Bcl-2 or Bcr-Abl oncoproteins, Bax, matrix metalloproteinases (MMP-2 and MMP-9) the androgen receptor, EGF receptor, Activator proteins 1(AP1), and some cell cycle regulators." (PMID 30701033, 2018). "It is believed that without functional ER, AR may be the primary driver that facilitate cancer progression." (PMID 28915596, 2017). "Other studies have shown expression of epithelial differentiation markers such as androgen receptor and prostate specific membrane antigen, hypoxia (carbonic anhydrase IX, hypoxia inducible factor 1α), and PTEN pathway activation are increased in higher grade cancers." (PMID 28552967, 2017). "AR and FOXA1 mRNA levels were significantly higher in ER-positive than in ER-negative tumors and AR-low/FOXA1-low tumors showed high grade, frequent basal-like subtype and worse disease-free survival in ER-positive cancers of public gene dataset, similarly to patient cohort results." (PMID 29137314, 2017). "Finally, the mutually exclusive overexpression between AR, HOXC6 and NKX2-2 is preserved across various tissues and cancers, suggesting that mutual exclusivity may represent an intrinsic characteristic of driver TFs during tumorigenesis." (PMID 28397780, 2017). "Additionally, in mouse recombinant models where patient cancer tissue is grown in the presence of either AR positive or negative fibroblasts, the apoptotic response of cancer cells to castration is significantly modulated by AR in the surrounding fibroblasts." (PMID 28117763, 2017). "This univariable analysis was useful for generating the hypothesis that AR signalling decreases with increasing cancer grade but is not definitive." (PMID 27120785, 2016). "We show that the chaperone function of CHKA confers a growth advantage on PCa by stabilizing the AR in addition to its well-known function in fuelling membrane production through the Kennedy pathway, suggesting a de facto role for CHKA as a rate-limiting factor in cancer cell growth." (PMID 26657335, 2016). "Without functional ER, AR may be the primary driver of downstream signaling and facilitate cancer progression." (PMID 27374089, 2016). "However, a study compared 20 molecular apocrine cancers with 26 non-apocrine cancers for AR expression and other clinical features." (PMID 27918430, 2016). "Moreover, we link for the first time Na+/K+ ATPase and mAR, a membrane androgen receptor mediating rapid, non-genomic anti-cancer effects of androgens in multiple cancer cells." (PMID 27027435, 2016). "While we have demonstrated interaction of SPDEF with the androgen receptor (AR) and various other proteins relevant for cancer signalling, no studies have been reported as of yet about the precise regulatory mechanisms of SPDEF protein expression and activity in the context of metastasis." (PMID 26885618, 2016). "Recent evidence suggests that the population of PCa cells in untreated primary tumors that survive ADT may expresses little/no AR (i.e., AR−/lo) and possesses many cancer stem cell (CSC) properties." (PMID 26871947, 2016). "Together these results indicate that efficient therapy for advanced stage PC would require simultaneous targeting of two types of cancer cell populations: those that are dependent on AR-signaling and the AR-independent (cells that are non-responsive to androgens) cancer stem-like cells." (PMID 25965834, 2015). "However, when analyzing the data for the cancer cells independently, the reduction of the RB gene expression signature (z = −2.46) and activation of the E2F1 signature (z = 2.34) were confirmed, and activation of the AR signature (z = 2.99) was significant." (PMID 25575823, 2015). "Interestingly, AR expression did not correlate with presence of NE cells or with biochemical recurrence, which is consistent with previous observations and suggests that NE cells do not influence AR expression in neighboring cancer cells." (PMID 25785244, 2015).
cancer (continued). "Additionally, a positive association between serum PSA levels was observed for AR content in cancer epithelia (p=0.004), but not with the other AR measures." (PMID 25965833, 2015). "Significant evidence suggests an important role for ACSLs in cancer biology including increased expression of ACSLs in many types of cancer such as colon, liver, lung, brain, and colorectal cancers and estrogen receptor negative breast tumors and androgen receptor negative prostate tumors." (PMID 25866768, 2015). "Such functional interactions between nuclear receptors and TFs, including the antagonistic interaction between RARs and AR and PPARδ, and the agonistic interaction between VDR and AR provide valuable information that can be used to improve cancer prevention and therapy." (PMID 24860512, 2014). "Furthermore, the S peptide does not affectserum-induced DNA synthesis or motility in NIH3T3 cells, and does notinterfere with serum-induced DNA synthesis and motility in AR-negative humanprostate cancer DU-145 cells." (PMID 25476896, 2014). "Moreover, in three independent patient samples, GAK and the AR did not colocalize with Ki-67, a cancer antigen that is found primarily in growing cells and is absent in resting cells." (PMID 24971999, 2014). "Thus in prostate, the androgen receptor promotes growth of cancer initiating cells via autonomous signalling pathways, whereas there is a lack and no apparent need for androgen receptor signalling in surrounding stroma." (PMID 23431470, 2013). "In the AR-absent/ER-negative subset, elevated androgen levels cannot stimulate cancer growth either directly or after conversion into estrogens, but they probably stimulate increased production of some other substance which is responsible for cancer growth through binding to its specific receptor." (PMID 23241075, 2012). "These issues associated with measuring CD133 and AR may also explain discrepancies between CD133+VE cancer stem cell studies where both the presence and absence of AR is reported." (PMID 23145034, 2012). "The ability of both Nrf1 and AR to respond to oxidative stress signaling and to regulate differentiation processes suggests that Nrf1 and AR might also be able to interact during differentiation in normal development or possibly during cancer progression." (PMID 24281119, 2010). "In cancer cells that express this mutant, low-level BPA exposure induced androgen-independent cellular proliferation, thereby indicating that in the context of AR-T877A, BPA exposure could potentially reduce therapeutic efficacy." (PMID 18007998, 2007). "Among 32 TCGA cancer types (LAML is not applicable in TIMER calculation), AR activity shows moderate-to-strong negative correlations (correlation coefficients ranging from −0.4 to −0.8) with the abundance of these six immune cell types in 19 cancers as estimated by TIMER." (PMID 41486951, 2026). "Therefore, the effect of 1 might not be dependent on AR, 1 might suppress proliferation and metastasis in PCa by disrupting other key cancer signaling pathways like mTOR/AKT and STAT3." (PMID 40374533, 2025). "Additionally, it has been reported that AR expression is significantly lower in poorly differentiated laryngeal SCC and cases with lymphatic invasion, indicating low AR may promote more aggressive carcinoma progression." (PMID 39744510, 2025).
cancer (continued). "Moreover, the AR IHC scores in left-sided non-cancerous tissues were equal between both age groups in men, as well as in females ≥ 60 years during the early and late-stage cancers." (PMID 37206439, 2023). "Given the shared binding DNA motifs that ER, AR, and other steroid hormone receptors have in common, this observation suggests that ER-targeted drugs might prove useful for patients with castrate-resistant DSRCT and, plausibly, the small minority of women that acquire this rare cancer type." (PMID 35650195, 2022). "As Sp1 and Sp3 are overexpressed in most cancer types, have been characterized as non-oncogene addiction genes, and have been studied as potential biomarkers for recurrent PCa, these key findings highlight the importance of examining the AR, Sp1 and Sp3 signaling axis in PCa." (PMID 35018219, 2022). "However, prostatic, adrenal, and intratumoral androgens also have a considerable role in resistance because a small overexpression of AR can compensate for the lack of androgen with withdrawal, sensitizing the cancer cells to small amounts of androgen ligand in order to sustain AR signaling." (PMID 36430730, 2022). "As a result, centrosome declustering drugs comprise a highly promising class of nontoxic, cancer-cell-selective therapeutic agents that ought to be used in any scenario wherein hypoxic conditions are likely to occur including in combination with AR-targeting therapies for TNBC." (PMID 36012111, 2022). "To study the detailed mechanism between AR and HCC, and find a new pathway to provide new strategies to better suppress HCC progression, we focused on miRNAs, for the reason that many papers have reported that miRNAs might play important roles in the regulation of progression of many cancers." (PMID 34745992, 2021). "Furthermore, the mutual inhibition between ZEB1 and AR may only be true for PCa cells, but not for other cancers." (PMID 33652914, 2021). "However, in cancer, the carcinogenic mechanism of KDM4B is due to an abnormal increase in its expression, resulting in activation of multiple oncogene signaling pathways by histone demethylation, such as binding with MYC, AR or ER to promote the expression of downstream genes." (PMID 35186950, 2021). "Importantly, regulation of the PPP by AR-SREBP1-6PGD has a broader clinical implication; therapeutic strategies that effectively suppress this pathway would impinge on the activity of three important oncogenic drivers with multifaceted cancer-promoting activities." (PMID 34382934, 2021). "The inhibitory effects of IL1β and the positive correlation of IL1R1 levels with AR activities in LNCaP, but not C4-2 cells, suggested an interplay between the inflammation and androgen signals in maintaining the homeostasis of androgen-sensitive prostate tissues and cancers." (PMID 33322099, 2020). "Besides, based on the analysis of cancer-related processes and pathways, KCNK family genes were involved in the activation or suppression of cell cycle, DNA damage response, epithelial-mesenchymal transformation, hormone AR/ER, PI3K, MAPK, RTK and mTOR signaling pathways." (PMID 32742463, 2020). "Moreover, AR expression was not a significant predictor of therapeutic response, though, suggestively, the superiority of monotherapy with letrozole relative to tamoxifen was more pronounced among women with AR−/ER+ cancers." (PMID 30795773, 2019). "We previously reported that the PCa-specific ability of betulinic acid (BA), a plant-derived small molecule, to decrease several pro-survival proteins including AR and increase cell death may be due to inhibition of multiple deubiquitinases (DUBs) in cancer but not in non-cancer cells." (PMID 30177856, 2018). "Therefore, all AR-negative NEPC type cancer specimens were excluded from our analysis." (PMID 29269934, 2017).
cancer (continued). "Based on this alternative hypothesis, disrupting the FABP5-PPARγ-VEGF signalling axis and cutting off the alternative energy supply of the cancer cells, rather than blocking the last drop of androgen, should be the correct way to kill the AR-negative CRPC cells." (PMID 26814431, 2016). "The functional interactions between AR and VDR, as well as other nuclear receptors and TFs may also be important for disease management, especially now that nutritional intervention has become more widely accepted as an effective approach to prevent cancer progression." (PMID 24860512, 2014). "It should be noted that the differentially expressed AR signaling genes in the cancer versus normal comparison of AA patients do not overlap with the corresponding set identified in the CA patients." (PMID 23365759, 2013). "Thus, cancers with N+C↓ AR expressed higher AKT1 levels, but this difference could not be detected on IHC due to abundant protein in all groups." (PMID 22114732, 2011). "Normal prostate epithelial cells (PNT2) and AR-negative CRPC cells (PC3) were insensitive to ITRI-148, highlighting potent and selective inhibition of cancer cell viability through AR targeting." (PMID 41237749, 2025). "Unlike its AR‐dependent ancestor, t‐NEPC remains a poor prognosis cancer, lacking effective treatment options, and thus necessitating the exploration and development of innovative therapies." (PMID 40013333, 2025). "The immunoprofile of our case (p40+, AR focal+, EBER-, p16 non-diffuse+) is pivotal, helping exclude LEC (EBER+), HPV-related carcinomas (p16+), and classic SDC (AR diffuse+)." (PMID 41404066, 2025). "Non-NE cancer cells exhibited higher Notch signaling activity (i.e., high HES1 and NOTCH1/2 expression) and higher nuclear AR levels." (PMID 39024561, 2024). "The AR expression at the mRNA and protein levels was oppositely correlated with RBM when compared with non-RBM cancer." (PMID 39585048, 2024). "These cancers are a form of CRPC and are especially hard to treat since the androgen receptor is absent and oncogenic signaling is activated through many other modalities." (PMID 38213538, 2023). "However, beyond a direct inhibition of cellular proliferation, it is possible that BAT can alter other cellular behaviors that promote cancer fitness, such as invasion, metastasis, and evasion of the immune system, which may or may not be dependent on cancer cell AR activity." (PMID 36194476, 2022). "The observation that AC016745.3 only partially restores the function of NONO in PCa cells suggests that the cancer-promoting properties of NONO are only partly driven by AR activity, and that other AR/AC016745.3-independent mechanisms must also exist." (PMID 34833084, 2021). "Interdependence of AR and FASN drives AR-dependent CRPC progression, but overexpression of FASN is the rule rather than the exception in many types of cancers." (PMID 33163409, 2020). "Immunoblot analysis revealed that HOXB13 is expressed in AR positive PC cell lines of luminal epithelial origin as well as in AR negative PC3, a cancer of small cell origin." (PMID 31273254, 2019). "Another multi-DUB inhibitor, WP113027, also reduced AR protein, increased poly-Ub/cell death, and decreased DUB activity in PCa but not in non-cancer prostate epithelial cells." (PMID 30177856, 2018). "Here, we demonstrate that, unlike the canonical transcriptional repressor and its functions in cancer stem cells, BMI1 performs its noncanonical function as a transcriptional activator and an AR cofactor." (PMID 29402932, 2018). "Regarding the association of AR/FOXA1 status with HER2 in the present study, TMA analysis and public dataset showed no statistical significance in ER-positive cancers, although decreased HER2 protein was noted by experiments overexpressing AR or FOXA1." (PMID 29137314, 2017).
cancer (continued). "When ccRCCs were categorized based on AR expression, univariate survival analysis revealed an increase in cancer-specific survival (CSS HR, 0.54; 95% CI, 0.38–0.76) in patients affected by tumors positive for AR compared to tumors with low/no AR expression." (PMID 29108248, 2017). "Overall, we found an inverse correlation between AR and AMACR in cancer cells (Pearson r = −0.26, p < 0.00001), but not in benign luminal cells (r = −0.05, p < 0.00001)." (PMID 29138507, 2017). "Cancer drivers and AD genes are enriched for high participation roles (kinless, and kinless hub, and connector in the case of drivers in ACMS PIN), while AR genes do not play a preferential role." (PMID 27080396, 2016). "Thus, we speculate that testosterone treatment may have played a role in the initiation of cancer in the colon tissue of the proband, probably exerting a direct interaction with the poorly or non-functional cytosolic AR protein or an indirect action through the membrane AR protein." (PMID 27267075, 2016). "A subset of EPCATs is Androgen Receptor or ERG regulated, but for most novel transcripts their unique transcriptional regulation in cancer is still not fully resolved and poses a new challenging research question." (PMID 25686826, 2015). "Although there were data available for ChIP-seq of androgen receptor (AR), FOXA1 and NKX3-1, data for TCF7L2— another transcription factor with a proposed role in prostate- and other cancers — was not available." (PMID 24497837, 2014). "We further investigated the effects of FOXA1 and AR on migration and invasion of EC cells, and found that neutralization of AR activity did not inhibit FOXA1-enhanced cancer cell migration or invasion." (PMID 24512546, 2014). "Therefore, the use of AR inhibition is a potential new therapeutic option for AR-positive TNBC and for the treatment of AR-negative TNBC, especially in combination with cancer immunotherapy." (PMID 39598525, 2024). "Targeting cancer epithelium is feasible, and we previously evaluated the anti-proliferation effect of enzalutamide in lung squamous carcinoma cell lines, but still have not investigated ZNF536 regulation of AR signaling pathway." (PMID 38720348, 2024). "There is a negative correlation between AR and PDE4B in cancer." (PMID 37830741, 2023). "However, it should be noted that coregulator expression changes with disease and that AR signalling is not confined to cancer cells, thus drugs targeting coregulators may have different effects with disease progression and may affect AR signalling in non-cancer tissue with unknown consequences." (PMID 37435460, 2022). "Androgen receptor (AR) blockade has thus far not shown therapeutic benefits for HCC79,121,122, but as we improve understanding of the biological pathways involved in driving cancer, this strategy warrants further exploration." (PMID 36212217, 2022). "However, if the cells are not dependent on AR, NRF2 activation will not be helpful when combined with ADT, rather, NRF2 activation will likely promote cancer cell survival by lowering ROS-mediated cellular damage." (PMID 36213236, 2022). "KAT2A has also been shown to play a critical role in carcinogenesis and the progression of several cancers; however, there are no reports of the impact of KAT2A on the non-histone acetylation of AR, and its potential role in primary or secondary resistance to abiraterone." (PMID 34381019, 2021). "AR expression is positively correlated with HER2 expression; it was shown that AR presence has beneficial effects only in tumors expressing HER, with no influence on outcome of HER2- luminal B cancers." (PMID 34638264, 2021). "With the exception of three clusters of NRs representing NR classes I (cluster I: RORC, VDR, PPARA, NR1D1, THRA, RORA, NR1H3; cluster II: RARB, PPARG, THRB) and III (cluster III: ESR1, PGR, AR, ESRRG), NR class was not a good determinate of NR expression patterns in the different cancer types." (PMID 32024906, 2020).